HNRNPU (heterogeneous nuclear ribonucleoprotein U)
Description:
DNA- and RNA-binding protein involved in several cellular processes such as nuclear chromatin organization, telomere-length regulation, transcription, mRNA alternative splicing and stability, Xist-mediated transcriptional silencing and mitotic cell progression. Plays a role in the regulation of interphase large-scale gene-rich chromatin organization through chromatin-associated RNAs (caRNAs) in a transcription-dependent manner, and thereby maintains genomic stability. Required for the localization of the long non-coding Xist RNA on the inactive chromosome X (Xi) and the subsequent initiation and maintenance of X-linked transcriptional gene silencing during X-inactivation (By similarity). Plays a role as a RNA polymerase II (Pol II) holoenzyme transcription regulator. Promotes transcription initiation by direct association with the core-TFIIH basal transcription factor complex for the assembly of a functional pre-initiation complex with Pol II in a actin-dependent manner. Blocks Pol II transcription elongation activity by inhibiting the C-terminal domain (CTD) phosphorylation of Pol II and dissociates from Pol II pre-initiation complex prior to productive transcription elongation. Positively regulates CBX5-induced transcriptional gene silencing and retention of CBX5 in the nucleus. Negatively regulates glucocorticoid-mediated transcriptional activation. Key regulator of transcription initiation and elongation in embryonic stem cells upon leukemia inhibitory factor (LIF) signaling (By similarity). Involved in the long non-coding RNA H19-mediated Pol II transcriptional repression. Participates in the circadian regulation of the core clock component BMAL1 transcription (By similarity). Plays a role in the regulation of telomere length. Plays a role as a global pre-mRNA alternative splicing modulator by regulating U2 small nuclear ribonucleoprotein (snRNP) biogenesis. Plays a role in mRNA stability. Component of the CRD-mediated complex that promotes MYC mRNA stabilization. Enhances the expression of specific genes, such as tumor necrosis factor TNFA, by regulating mRNA stability, possibly through binding to the 3'-untranslated region (UTR). Plays a role in mitotic cell cycle regulation. Involved in the formation of stable mitotic spindle microtubules (MTs) attachment to kinetochore, spindle organization and chromosome congression. Phosphorylation at Ser-59 by PLK1 is required for chromosome alignement and segregation and progression through mitosis. Also contributes to the targeting of AURKA to mitotic spindle MTs. Binds to double- and single-stranded DNA and RNA, poly(A), poly(C) and poly(G) oligoribonucleotides. Binds to chromatin-associated RNAs (caRNAs). Associates with chromatin to scaffold/matrix attachment region (S/MAR) elements in a chromatin-associated RNAs (caRNAs)-dependent manner. Binds to the Xist RNA. Binds the long non-coding H19 RNA. Binds to SMN1/2 pre-mRNAs at G/U-rich regions. Binds to small nuclear RNAs (snRNAs). Binds to the 3'-UTR of TNFA mRNA. Binds (via RNA-binding RGG-box region) to the long non-coding Xist RNA; this binding is direct and bridges the Xist RNA and the inactive chromosome X (Xi) (By similarity). Also negatively regulates embryonic stem cell differentiation upon LIF signaling (By similarity). Required for embryonic development (By similarity). Binds to brown fat long non-coding RNA 1 (Blnc1); facilitates the recruitment of Blnc1 by ZBTB7B required to drive brown and beige fat development and thermogenesis (By similarity). (Microbial infection) Negatively regulates immunodeficiency virus type 1 (HIV-1) replication by preventing the accumulation of viral mRNA transcripts in the cytoplasm.
Synonyms: hnRNP U; SAF-A; HNRPU; SAFA; U21.1; FLJ37978; FLJ30202; DEE54; EIEE54; GRIP120; HNRNPU-AS1; pp120; formerly C1orf199; NCRNA00201
Tractability: Antibody: UniProt places it where antibodies can reach, with high confidence. PROTAC: UniProt records ubiquitination sites on it; ubiquitination databases record sites on it; its protein half-life has been measured.
Gene: Protein-coding gene on chromosome 1 (244,840,638 to 244,864,560, reverse strand). Ensembl gene ENSG00000153187.
Subcellular location: Nucleus; Nucleus matrix; Chromosome; Nucleus speckle; Cytoplasm, cytoskeleton, microtubule organizing center, centrosome; Chromosome, centromere, kinetochore; Cytoplasm, cytoskeleton, spindle; Cytoplasm, cytoskeleton, spindle pole; Midbody; Cytoplasm; Cell surface; Cytoplasmic granule
Subcellular location (Human Protein Atlas): Nucleoplasm
Pathways (Reactome):
Metabolism of RNA: Processing of Capped Intron-Containing Pre-mRNA; mRNA Polyadenylation; mRNA Splicing - Major Pathway
Developmental Biology: Transcriptional regulation of brown and beige adipocyte differentiation by EBF2
Disease: Dengue Virus-Host Interactions
Gene Ontology:
Molecular function: actin binding; ATP binding; chromatin binding; chromatin DNA binding; DNA binding; double-stranded DNA binding; double-stranded RNA binding; identical protein binding; mRNA 3'-UTR binding; piRNA binding; poly(A) binding; poly(C) RNA binding; poly(G) binding; pre-mRNA binding; protein binding; protein-containing complex binding; ribonucleoprotein complex binding; RNA binding; RNA polymerase II complex binding; sequence-specific double-stranded DNA binding; single-stranded DNA binding; single-stranded RNA binding; snRNA binding; telomerase RNA binding; TFIIH-class transcription factor complex binding; and 6 more
Biological process: cellular response to glucocorticoid stimulus; CRD-mediated mRNA stabilization; maintenance of protein location in nucleus; mRNA stabilization; negative regulation of kinase activity; negative regulation of nuclear-transcribed mRNA catabolic process, deadenylation-dependent decay; negative regulation of stem cell differentiation; negative regulation of telomere maintenance via telomerase; negative regulation of transcription by RNA polymerase II; negative regulation of transcription elongation by RNA polymerase II; osteoblast differentiation; positive regulation of attachment of mitotic spindle microtubules to kinetochore; positive regulation of cytoplasmic translation; positive regulation of transcription by RNA polymerase II; protein localization to spindle microtubule; random inactivation of X chromosome; regulation of alternative mRNA splicing, via spliceosome; regulation of chromatin organization; regulation of mitotic cell cycle; regulation of mitotic spindle assembly; regulatory ncRNA-mediated heterochromatin formation; adaptive thermogenesis; alternative mRNA splicing, via spliceosome; cellular response to leukemia inhibitory factor; chromatin organization; and 10 more
Cellular component: catalytic step 2 spliceosome; cell surface; centrosome; chromosome; CRD-mediated mRNA stability complex; cytoplasm; cytoplasmic ribonucleoprotein granule; cytosol; inactive sex chromosome; kinetochore; membrane; midbody; mitotic spindle; mitotic spindle microtubule; mitotic spindle midzone; nuclear chromosome; nuclear matrix; nuclear speck; nucleoplasm; nucleus; protein-containing complex; ribonucleoprotein complex; RNA polymerase II transcription regulator complex; telomerase holoenzyme complex; dendrite; and 2 more
Genetic constraint (gnomAD): Loss-of-function variants: 3 observed, 69.95 expected, observed/expected ratio (o/e) 0.0429, 90% interval 0.019 to 0.11. The upper end of that interval is the gene's LOEUF score, 0.11, which puts it in group 1 of 6, group 1 being the genes least tolerant of losing a copy. Missense variants: 627 observed, 918.42 expected, observed/expected ratio (o/e) 0.68, 90% interval 0.64 to 0.73. Synonymous variants: 391 observed, 353.4 expected, observed/expected ratio (o/e) 1.11, 90% interval 1.02 to 1.2.
Gene-disease validity (ClinGen):
ClinGen rates the evidence that HNRNPU causes each of these diseases.
complex neurodevelopmental disorder (autosomal dominant): Definitive. A disorder that involves more than one phenotype associated with the central nervous system, including but not limited to intellectual disability, autism, and seizures (epilepsy).
Homologues: Orthologues: chimpanzee HNRNPU (100% identical), macaque HNRNPU (99% identical), guinea pig HNRNPU (98% identical), rabbit HNRNPU (97% identical), pig HNRNPU (96% identical), dog HNRNPU (95% identical), mouse Hnrnpu (94% identical), rat Hnrnpu (92% identical), tropical clawed frog hnrnpu (70% identical), zebrafish hnrnpub (56% identical), zebrafish hnrnpua (51% identical). Paralogues in human: HNRNPUL1 (42% identical), HNRNPUL2 (37% identical).
Diseases named in the same sentence as HNRNPU in open-access papers:
HNRNPU is named in the same sentence as 106 diseases in open-access papers, as found by Europe PMC text mining. Sharing a sentence is not in itself a finding about the gene and the disease. The quoted sentences say what the papers report.
Intellectual disability (11 papers, 2017 to 2026). "In humans, mutations in the heterogeneous nuclear ribonucleoprotein U (HNRNPU) gene cause early-onset epilepsy, autistic features and intellectual disability." (PMID 40335689, 2025). "Microdeletions in the 1q44 locus encompassing HNRNPU and other genes and point mutations in HNRNPU cause brain disorders, including early-onset seizures and severe intellectual disability." (PMID 35864088, 2022). "Patients with HNRNPU variants show moderate‐to‐severe intellectual disability, as well as epileptic seizures that are mainly generalized such as tonic, atonic, and absence seizures." (PMID 32913952, 2020). "The deficiency of HNRNPU, linked to neurodevelopmental disorders, impacted chromatin structure, transcriptional rewiring, and exon usage during mRNA processing, particularly enriching genes associated with epilepsy, intellectual disability, and autism." (PMID 37815090, 2023). "Mutations in both hnRNPU and SYNCRIP are linked to intellectual disability and neurodevelopmental disorders, and were the two top candidates in an IBM Watson-based study to identify RBPs altered in amyotrophic lateral sclerosis (ALS)." (PMID 39937575, 2025). "Microdeletions of HNRNPU have been described in individuals with intellectual disability and other clinical features, such as seizures, corpus callosum abnormalities and microcephaly." (PMID 30526634, 2018). "Our study demonstrates that AKT3 haploinsufficiency is the main driver for microcephaly, whereas HNRNPU alteration mostly drives epilepsy and determines the degree of intellectual disability." (PMID 28283832, 2017).
breast carcinoma (10 papers, 2015 to 2025). "The high protein expression of hnRNPU was associated with a poor overall survival time in breast cancer patients." (PMID 35954396, 2022). "The high mRNA expression of hnRNPU was associated with a poor overall survival time in breast cancer patients." (PMID 35954396, 2022). "HNRNPU is a splicing factor which recently has been implicated in APA of CD55 in breast cancers." (PMID 39188787, 2024). "Previous studies on hnRNPU in cancer have primarily focused on its proliferative properties in breast cancer, hepatocellular carcinoma, multiple myeloma, and bladder cancer." (PMID 39773744, 2025). "Our CHIP-seq and CHIP-qPCR data showed a similar pattern in breast cancer cells.: HNRNPU and DDX5 are enriched in the TSS of LMO4 and then activate LMO4 transcription." (PMID 36347834, 2022). "The TCGA and METABRIC (Molecular Taxonomy of Breast Cancer International Consortium) databases demonstrated that HNRNPU was highly expressed in basal-like breast cancers." (PMID 36347834, 2022). "Overall, our study innovatively elucidated that HNRNPU induces the proliferation and migration of TNBC cells in vivo and in vitro and that HNRNPU is associated with a poor prognosis in breast cancer patients." (PMID 36347834, 2022). "We assessed the expression of HNRNPU in other breast cancer cell lines, and high expression was found in MDA-MB-231 cell lines." (PMID 36347834, 2022). "Mechanistically, we found that in breast cancer CDC20-mediated hnRNPU ubiquitination regulates the formation of the CTCF–RAD21 complex, two proteins involved in the formation of chromatin loops." (PMID 35954396, 2022). "Both in vitro and in vivo experiments demonstrated that HNRNPU can function as an oncogene to promote breast cancer cell proliferation and migration." (PMID 36347834, 2022). "To determine the role of hnRNPU in breast cancers, we measured the expression of hnRNPU in normal breast epithelial, DCIS, and different breast cancer cell lines, including TNBC, HER2+, and Luminal subtypes." (PMID 35954396, 2022). "Remarkably, HNRNPU is upregulated in breast cancer, especially in TNBC, and the high expression of HNRNPU indicates a poor prognosis." (PMID 36347834, 2022). "Further determination of the physiological impact of hnRNPU in breast carcinogenesis and anti-cancer drug resistance using preclinical breast cancer models will confirm our documented oncogenic effect for hnRNPU in breast cancer." (PMID 35954396, 2022). "The immunohistochemistry (IHC) staining analysis of the breast cancer tissue microarrays showed that the expression of HNRNPU was higher in TNBC than in other molecular subtypes." (PMID 36347834, 2022). "We showed that the expression levels of hnRNPU in human breast cancer tissues are significantly high." (PMID 35954396, 2022). "We showed that CDC20 interacts with hnRNPU in the chromatin fraction and regulates its ubiquitination in breast cancer cells." (PMID 35954396, 2022). "Next, we further explored whether the expression of HNRNPU was clinically relevant to breast cancer patients." (PMID 36347834, 2022). "Additionally, hnRNPU has been shown to promote breast cancer cell proliferation, migration, and invasion." (PMID 35954396, 2022). "Additionally, a strong correlation between CDC20 and hnRNPU expression in breast cancer patients was shown by using correlationAnalyzerR." (PMID 35954396, 2022). "However, the function and tumorigenic role of HNRNPU in breast cancer have rarely been reported, so this finding attracted our interest." (PMID 36347834, 2022). "The role of HNRNPU in alternative splicing regulation was unclear in breast cancer until now." (PMID 36347834, 2022). "Therefore, investigation of hnRNPU regulation in breast cancer circumstances and the development of related targeting strategies could lead to a new anticancer therapy." (PMID 35954396, 2022). "Therefore, our research showed that HNRNPU serves as an oncogene in breast cancer." (PMID 36347834, 2022).
breast carcinoma (continued). "Moreover, hnRNPU promotes breast cancer cell proliferation, migration, and invasion." (PMID 35954396, 2022). "Our investigation showed that HNRNPU could promote the proliferation and migration of breast cancer cells in vitro and vivo, and this has been verified in patient data showing that the expression of HNRNPU in cancer tissues was higher than that in adjacent tissues." (PMID 36347834, 2022). "For the first time, this paper puts forward that HNRNPU and PEX19 are related to the prognosis of dendritic cells in cancer, which also provides new possibilities for finding new targets for breast cancer immunotherapy." (PMID 36835467, 2023). "For the first time, this paper proposes that HNRNPU and PEX19 are related to the prognosis of DCs in cancer, which also provides new possibilities for finding new targets for breast cancer immunotherapy." (PMID 36835467, 2023). "Among all the RBPs (HNRNPU, HNRNPK, RBM5, HNRNPLL, HNRNPH1, HNRNPM, HNRNPA2B1) screened, only SRSF7 (also known as 9G8) was substantially upregulated in hypoxia-treated breast cancer cells." (PMID 34362878, 2021). "While some of these spliceosome genes, such as SNRPA1, SNRPD1, USP39, HNRNPU, and HNRNPC, have been shown to play an important role in promoting TNBC cell survival, proliferation, and response to chemotherapy, others are yet to be studied in breast cancer." (PMID 39418101, 2024). "We did not see a significant difference in hnRNPU levels in breast cancer cells with CDC20 overexpression or knockdown." (PMID 35954396, 2022). "In this study, we analysed RNA-seq data in HNRNPU knockout and DDX5 knockdown breast cancer cells." (PMID 36347834, 2022). "The Cancer Genome Atlas (TCGA) database and our single-centre database (Fudan University Shanghai Cancer Center database, FUSCC-database) showed that the mRNA expression of HNRNPU was upregulated in breast cancer tissues compared with noncancer tissues." (PMID 36347834, 2022). "We observed that several genes, specifically RRM2B, HNRNPU, Dux4, SYNCRYP, and WISP-1 are regulated in a similar fashion in tubular epithelial cells as in breast cancer cells whereas remaining genes have not shown similar regulation (data not shown)." (PMID 29254187, 2017).
epilepsy (10 papers, 2017 to 2025). A brain disorder characterized by episodes of abnormally increased neuronal discharge resulting in transient episodes of sensory or motor neurological dysfunction, or psychic dysfunction. "Upon review, her phenotype is more severe and is consistent with HNRNPU-associated epilepsy, which is likely genetically distinct from the epilepsy in other family members." (PMID 38101940, 2024). "We identified CNVs covering recently reported (HNRNPU) or emerging (RORB) epilepsy genes, and further delineated the phenotype associated with mutations of these genes." (PMID 30866059, 2019). "Interestingly, genes mapping in the enriched B compartments are associated with ASD and epilepsy, suggesting that the chromatin remodeling dependent on HNRNPU expression might ultimately be the driver of the observed phenotypes." (PMID 37815090, 2023). "Of the 36 patients with epilepsy, 35 had a deletion including HNRNPU and only one had a deletion sparing HNRNPU (p = 1.28E−8)." (PMID 28283832, 2017). "The minimal critical region for epilepsy was narrow and included HNRNPU and COX20, which is a gene that tolerates haploinsufficiency." (PMID 28283832, 2017). "Our data confirm that AKT3 is the main gene driving microcephaly, ZBTB18 defect is responsible for AnCC and HNRNPU is the main gene accounting for epilepsy." (PMID 28283832, 2017). "A deletion encompassing HNRNPU was identified in the proband of a multiplex family; segregation studies showed that the deletion occurred de novo, suggesting that other genetic factors must be contributing to the epilepsy in the extended family." (PMID 38101940, 2024). "We also identified CNVs affecting monogenic epilepsy genes, including four families with CNVs disrupting the DEPDC5 gene, and a de novo deletion of HNRNPU in one affected individual from a multiplex family." (PMID 38101940, 2024). "The HNRNPU (heterogeneous nuclear ribonucleoprotein U) and the FAM36A (family with sequence similarity 36, also known as COX20—cytochrome c oxidase assembly factor) genes, were proposed as good candidates for the epilepsy and ID phenotype within the 1q43-q44 microdeletion syndrome." (PMID 30853971, 2019).